EGFR (epidermal growth factor receptor)
Diseases named in the same sentence as EGFR in open-access papers (continued):
Sharing a sentence is not in itself a finding about the gene and the disease.
colorectal cancer (continued). "Recent data have shown that it correlates with a decrease in EGFR phosphorylation, decreased invasion, lower nodal involvement, reduced subsequent metastasis, and longer disease-free and overall survival in stage II/III colorectal carcinoma patients who have received curative surgery." (PMID 18544172, 2008). "A monoclonal antibody directed at the epidermal growth factor receptor (EGFR), cetuximab, has been approved by the U.S. Food and Drugs Administration for the treatment of patients with colorectal cancer who no longer respond to standard chemotherapy treatment with irinotecan." (PMID 21614218, 2006). "The effectiveness of EGFR (epidermal growth factor receptor) and VEGFR (vascular endothelial growth factor receptor) inhibitors faces limitations in KRAS wild-type colorectal carcinoma (CRC)." (PMID 38844562, 2024). "This comprehensive study provides a detailed overview of the historical advancements in EGFR/VEGFR antibodies and delves into recent progress concerning several signaling pathways intricately involved in the tumorigenesis of colorectal carcinoma (CRC)." (PMID 38844562, 2024). "In drug-resistant cells of colorectal cancer, the aberrantly expressed SENP1 could increase the SUMOyaltion of HIF-α, which leads to the conversion of intracellular signal transduction pathway from Wnt/β-catenin to EGFR/IKKα/β/NF-kB, thus reducing the sensitivity of cancer cells to irinotecan." (PMID 37777749, 2023). "EGFR expression has also been studied using panitumumab labeled with [89Zr]Zr-Panitumumab is a completely humanized mAb that binds to the EGFR, and it is FDA (Food and Drug Administration)-approved for use in receptor expressing colorectal cancers without KRAS mutations." (PMID 38136430, 2023). "However, on the other hand, about 50% of patients with wild-type KRAS colorectal cancer may not respond to anti-EGFR therapies." (PMID 33946899, 2021). "However, the anti-EGFR targeting antibody Cetuximab could not influence the overall survival as shown in a study of second-line treatment of colorectal cancer." (PMID 34360915, 2021). "Furthermore, EGFR inhibition by erlotinib, a small molecule inhibitor that binds to the intracellular tyrosine kinase domain, or treatment with oxaliplatin, a chemotherapy used to treat colorectal cancer, did not initiate increased secretion of EGF." (PMID 32481658, 2020). "In our previous work, we determined that RHBDD1 was highly expressed in colorectal cancer tissues but weakly expressed in adjacent normal tissues, and could activate the EGFR/Raf/MEK/ERK signaling pathway through the cleavage and secretion of TGFα as well as up-regulation of EGFR expression." (PMID 30286765, 2018). "Recent data on colorectal cancer suggested that one of the molecular mechanisms responsible of primary and acquired resistance to anti-EGFR therapies is the activation of MEK/MAPK and that the simultaneous inhibition of EGFR and MEK/MAPK could overcome this resistance." (PMID 27429047, 2016). "The OPUS and CRYSTAL studies of colorectal cancer patients receiving the FOLFOX plus cetuximab and FOLFIRI plus cetuximab regimens, respectively, have demonstrated that mutations in codons 12 and 13 are negative predictive factor for the response to the anti-EGFR antibody cetuximab." (PMID 25954997, 2015). "Similar to the reported 7.7% allele frequency in Chinese colorectal cancer patients, we found an incidence of MLH1 V384D around 7-8% in tumors with wild-type or L858R mutant EGFR, suggesting that MLH1 V384D may not be a mutation secondary to the EGFR L858R mutation." (PMID 25823662, 2015). "In addition to EGFR, several important glycoproteins, such as MET, insulin-like growth factor-2 receptors (IGF-2R), and vascular endothelial growth factor receptor 2 (VEGFR2), also contain N-glycans and play critical roles in the pathogenesis of colorectal cancer." (PMID 25003232, 2014).
colorectal cancer (continued). "It is known that there are positive and negative feedback loops within EGFR-mediated pathways depending on cell type, and one reason for better prognosis in colorectal cancer may be that binding of TATI leads to inhibition of cascades leading to malignant transformation." (PMID 24204699, 2013). "Therefore, tactics targeting EGF/EGFR cascade system would have been an effective and timely approach for clinical prevention and therapeutic intervention for the transition from chronic non-resolving UC to pernicious colorectal carcinoma." (PMID 23825635, 2013). "However, data regarding the in vivo EGFR-driven molecular profile in colorectal cancer are conflicting and consequently at the present no speculations are possible about its role in determining resistance and/or sensitivity to EGFR-targeted drugs." (PMID 22490361, 2012). "However, data regarding the in vivo EGFR-driven molecular profile in colorectal cancer are conflicting and consequently, at present, no speculations are possible about its role in determining resistance or sensitivity to EGFR-targeted drugs." (PMID 17579627, 2007). "While drugs targeting EGFR and VEGFA have been extensively studied for colorectal cancer, there are currently no reported drugs for this disease targeting CHI3L1." (PMID 38177294, 2024). "IHC data confirmed that EGFR and MUC1 were highly expressed on LUAD and colorectal cancer (CRC) clinical samples but not on various normal tissues." (PMID 39664199, 2024). "EGF-liposome conjugates remarkably reduced the IC50 value of oxaliplatin in colorectal cancer cells which overexpressed ERFR, though not in the EGFR-negative colorectal cancer cells." (PMID 36983571, 2023). "Although anti-EGFR antibodies are likely to be used in the first-line treatment of RAS wild-type, left-sided colorectal cancer, there is no clear evidence for the efficacy of angiogenesis inhibitors in subsequent second-line treatment." (PMID 37760533, 2023). "Nonetheless, MARM2.0 is applicable not only to BRAFV600E melanoma cells (with and without EGFR overexpression) under a wide variety of conditions but also, with small modifications, to BRAFV600E NRASQ61K melanoma and BRAFV600E colorectal cancer cells." (PMID 36700386, 2023). "RAS mutations are identified in about half of patients diagnosed with colorectal cancer, conferring poor prognosis and lack of response to the anti-EGFR (epidermal growth factor receptor) therapy." (PMID 36674440, 2023). "Negative results for the EGFR-driven cell lineHCC827 and the KRAS-driven patient-derived colorectal cancer xenograftPDX-pY-IP are presented for comparison." (PMID 37053475, 2023). "Western blot analysis displayed that CEA expression was not affected by onalespib treatment in any of the assessed colorectal cancer cell lines, while known HSP90-related markers, such as EGFR and AKT1,2,3, displayed alterations." (PMID 35433442, 2022). "To study the interplay between nutrition and intestinal metabolism in the context of colitis-driven colorectal carcinoma (CRC), we here investigated a nutritional therapy strategy in the presence or absence of EGFR-directed antibody therapy in mice to treat established colitis-driven CRCs in vivo." (PMID 34830971, 2021). "In fact, anti-EGFR antibodies, cetuximab and panitumumab, are prescribed exclusively for wild-type RAS/RAF colorectal cancer patients, not for RAS/RAF mutants." (PMID 32708005, 2020). "In another report, the same dual β1-integrin/EGFR inhibition approach, as well as KRAS or BRAF depletion and 5-FU-treatment failed to modulate the radiosensitivity of colorectal carcinoma cells." (PMID 32903756, 2020). "The present study focuses on the involvement of EGFR positive and negative feedback genes in the establishment of cetuximab (CTX) resistance in metastatic Colorectal Cancer (CRC) patients." (PMID 31052457, 2019).
colorectal cancer (continued). "Moreover, low EZH2 expression was associated with a shorter PFS in patients with colorectal cancer, independent of gene mutations in the downstream part of the EGFR pathway and miR-31 expression, suggesting that EZH2 expression is a useful and additional prognostic biomarker for anti-EGFR therapy." (PMID 28147317, 2017). "Stiff substrates enhanced colorectal cancer cell viability by upregulating MMP-7 expression through a positive feedback loop containing YAP, EGFR, integrin-α2β1 and MRLC, independent of Hippo pathway." (PMID 27765911, 2016). "A previous study has demonstrated a significant correlation between the absence of EGFR methylation and the response to CTX-based chemotherapy in colorectal cancer patients." (PMID 25663927, 2015). "Adding Cetuximab (Erbitux; ImClone Systems Inc.), a monoclonal antibody and inhibitor of EGFR, to multimodal treatment increased efficiency of anticancer therapy in patients with k-RAS wild type non-resectable liver metastasis originally from colorectal carcinoma (CRC)." (PMID 24629025, 2014). "However, unlike NSCLC or colorectal cancer, GBM remains virtually irresponsive to EGFR-targeting therapies." (PMID 39273661, 2024). "Importantly, the efficacy of BMS-986351 and cetuximab in colorectal cancer cell lines with KRAS mutations represents a potential treatment opportunity for cetuximab-resistant tumors, given that the mechanism of action of BMS-986351 may be independent of EGFR pathway activity." (PMID 38319147, 2024). "The first approved, EGFR inhibitor erlotinib in combination with gemcitabine, gave a modest survival benefit compared to gemcitabine alone and was effectively abandoned by the community after negative data in KRAS-mutant colorectal cancer emerged." (PMID 37927794, 2023). "For example, Srx can modulate cancer cell motility via redox sensitive interaction with non-muscle myosin IIA (NMIIA) and S100A4, and promotes colorectal cancer cell adhesion and migration through a mechanism of enhancing EGFR (epidermal growth factor receptor) signaling." (PMID 28448437, 2017). "The FDA acknowledged the evidence base for KRAS presence as a marker for patients who would achieve no benefit from anti-EGFR therapy and issued a label update for the entire class of drugs, recommending KRAS testing as part of colorectal cancer patient management." (PMID 26858745, 2015). "Erlotinib, a tyrosine kinase inhibitor of EGFR, is approved for locally advanced or metastatic non-small cell lung cancer and locally advanced, unresectable, or metastatic pancreatic cancer, but is not currently FDA-approved for colorectal cancer." (PMID 25594061, 2014). "Although anti-EGFR antibodies are likely to be used in the first-line treatment of RAS wild-type, left-sided colorectal cancer, no conclusion has been reached as to whether the primary site influences the effect of anti-EGFR antibodies in previously treated patients." (PMID 37760533, 2023). "With EGFR upstream of RAS, inactivation of these receptor tyrosine kinases can in theory reduce RAS activation, and this linear model explains the lack of clinical activity for EGFR inhibitors in colorectal cancer in the setting of K-RAS or N-RAS-mutant tumours." (PMID 35582302, 2021). "Some genes, such as K-ras and epidermal growth factor receptor (EGFR) and human epidermal growth factor receptor 2 (HER2) are reported to be involved in the progress and development of colorectal cancer, but the LRIG1 roles in colorectal cancer have not been well studied and remained contradictory." (PMID 33461538, 2021). "This potentiating effect of FTY720 on EGFR kinase inhibition has not previously been reported, although a combination effect of FTY720 (used as an S1P receptor antagonist) and the EGFR monoclonal cetuximab has been reported in colorectal cancer cells and xenograft tumors." (PMID 28778177, 2017).
colorectal cancer (continued). "The use of anti-EGFR monoclonal antibodies (mAb anti-EGFRs) in colorectal cancer has shown that KRAS and NRAS represent the main resistance mechanisms to this type of treatment and are thus used in clinical practice to select the patients who should not be treated with anti-EGFR therapy." (PMID 27886225, 2016). "Although the mechanisms of this activation have not been clearly established in colorectal cancer (CRC), it could result from gain of copies of the EGFR gene, or overexpression of EGFR ligands that have both been suggested to be markers of sensitivity to anti-EGFR." (PMID 19367287, 2009).
glioma (1,860 papers, 1995 to 2026). A benign or malignant brain and spinal cord tumor that arises from glial cells (astrocytes, oligodendrocytes, ependymal cells). "The bithalamic high-grade glioma especially demonstrates EGFR mutations which makes it a distinct entity." (PMID 41596345, 2026). "In contrast, the development of IDH-wildtype gliomas relies on the synergistic activation of multistep oncogenic pathways, such as EGFR amplification and TERT promoter mutation." (PMID 41602776, 2026). "Other gene functions implicated in glioma risk in this study include signal transduction (e.g. EGFR), cell adhesion (e.g. GJB2), immune response (e.g. IFIH1 and SAMHD1), and ion transport (e.g. CFTR)." (PMID 41546701, 2026). "Scutellarin and lidocaine exerted a synergistic effect on suppressing the proliferation and migration and inducing the apoptosis of glioma cells, which was partly associated with the repression of EGFR signaling." (PMID 39888904, 2025). "Although IDH mutation status in newly diagnosed and recurrent gliomas can be reliably assessed using multi‐parametric MRI, the greater spatial and temporal variability of EGFR amplification complicates its imaging‐based characterization." (PMID 40197845, 2025). "The most frequent genetic lesions in GBM and high-grade gliomas include the mutation or amplification of the epidermal growth factor receptor (EGFR) tyrosine kinase coding genes." (PMID 40806617, 2025). "For three genes (HEATR3, PHLDB1 and RTEL1) there were both expression and splicing causal effects on glioma risk, and for one gene (EGFR) there were both expression and protein abundance causal effects on glioma risk)." (PMID 39565278, 2025). "In IDH1/2-wild-type gliomas, high frequencies of TERTp mutations (48.9%), EGFR amplifications (29.7%), PTEN alterations (27.9%), and chromosomal 7+/10− alterations (27.5%) correlated with advanced age and poor prognosis." (PMID 41377022, 2025). "In contrast, U87-EGFRvIII cells overexpress the constitutively active EGFR variant III (EGFRvIII) frequently associated with high-grade gliomas." (PMID 41425707, 2025). "The top KEGG-enriched pathways linked to imatinib include EGFR signaling, glioma, neurotrophin signaling, and various metabolic processes." (PMID 40732226, 2025). "Diffusion and perfusion MRI characterized IDH status in both newly diagnosed and recurrent gliomas, but showed limited diagnostic performance for EGFR, especially for recurrent tumors." (PMID 40197845, 2025). "Glioma-associated EGFR mutant forms display constitutive kinase activity, which drive cellular proliferation and migration by chronically stimulating Ras signaling." (PMID 40806617, 2025). "For example, the current WHO classification now subsumes midline gliomas with H3 K27M mutations together with gliomas showing aberrant EZHIP expression or with an EGFR mutation." (PMID 40647406, 2025). "In high-risk gliomas, recurrent CNVs—such as chromosome 7/12 amplifications (EGFR, CDK4/MDM2) and chromosome 1/8/13 deletions (CHD5, DLC1, RB1)—play pivotal roles in promoting proliferation, immune evasion, and DNA repair defects." (PMID 40636690, 2025). "Several genes included in our signature, notably NOTCH1, NES, E2F1 and EGFR, have been implicated in glioma adaptation to temozolomide (TMZ) therapy, where changes in their expression or activity influence stemness, invasion and drug resistance." (PMID 41375052, 2025). "Lower apparent diffusion coefficient (ADC) values, indicating higher cellularity, are associated with IDH‐wildtype and EGFR amplification in gliomas." (PMID 40197845, 2025). "Mechanistically, the effect of SCU and its combination with lidocaine on glioma cells was partially associated with the repression of EGFR signaling." (PMID 39888904, 2025).